EZH2 (enhancer of zeste 2 polycomb repressive complex 2 subunit)
Diseases named in the same sentence as EZH2 in open-access papers (continued):
Sharing a sentence is not in itself a finding about the gene and the disease.
lung cancer (continued). "However, cancer studies showed that EZH2 regulated TGFBR2 via the H3K27me3-dependent mechanism, by which hypoxia and YAP/TAZ signal attenuated TGFBR2 expression in prostate and lung cancer, respectively." (PMID 37710230, 2023). "It has been demonstrated that EZH2 could stimulate the expression of CCL5 and result in the recruitment of macrophages and the invasion of lung cancer." (PMID 37513975, 2023). "Further analysis also revealed that the expression of EZH2 was closely related to the pathologic stage or metastasis of LIHC, PRAD, KICH, KIRC, and lung cancer, suggesting that EZH2 could serve as one oncogene in tumor progression and metastasis." (PMID 36545914, 2023). "To investigate the 3D genome architecture and its regulatory function in lung cancer, we performed long-read ChIA-PET associated with CTCF, RNAPII, EZH2, and H3K27me3 in the lung cancer cell line A549 and noncancerous cell line BEAS-2B." (PMID 36702236, 2023). "We detected high levels of p-FAK expression in regions with high levels of EZH2 and H3K27me3 expression in lung-cancer-cells-derived tumor tissues but not in the normal tissue." (PMID 36009484, 2022). "Notably, EZH2 is the core subunit of the PRC2 complex, which can bind to lncRNA in lung cancer cells to regulate the expression of targeted genes." (PMID 35902569, 2022). "Epigenetic mechanisms could be involved in CCL2 repression in neuroblastoma, as recently described in lung cancer, where epigenetic silencing of CCL2 by DNMT1 and the EZH2/H3K27me3 axis potentiates tumor development by inhibiting macrophage infiltration." (PMID 36923280, 2022). "We explored whether FAK inhibition induces cellular senescence through an EZH2 inhibition-mediated pathway by treating lung cancer cells with a FAK inhibitor, PF-573228, and examining whether FAK inhibition affects EZH2 expression or function." (PMID 36009484, 2022). "For example, EZH2 is activated in many cancer types including LUAD and may serve as an opportunity for targeted therapy in lung cancer." (PMID 36304306, 2022). "EZH2 knockdown in mouse models of cancer or targeting EZH2 with specific inhibitors allowed restoration of MHC-I expression in melanoma, B cell lymphoma and lung cancer." (PMID 34201655, 2021). "EZH2 also maintains MHC-I epigenetic silencing in a subset of solid tumors including small cell lung cancer, neuroblastoma and Merkel cell carcinoma; EZH2 inhibition restored MHC-I expression in lung cancer via NLRC5 and IRF1 de-repression." (PMID 34201655, 2021). "Metformin suppressed the protein and mRNA expressions of euchromatic histone lysine methyltransferase 1, 2 (EHMT1, EHMT2), enhancer of zeste 1, 2 polycomb repressive complex 2 subunit (EZH1, EZH2), lysine methyltransferase 2A, 2B (MLL1, MLL2), and WD repeat domain 82 (WDR82) in lung cancer cells." (PMID 33578894, 2021). "Consistent with this hypothesis, siRNAs knockdown of KRAS greatly reduced cytoplasmic EZH2 in A549 cells, which have mutant KRAS, and increased DLC1 protein in A549 and four other lung cancer lines with mutant KRAS." (PMID 34862367, 2021). "EZH2, which is the catalytic subunit of PRC2, is often over-expressed in lung cancer." (PMID 34692550, 2021). "Finally, hsa-mir-144 impacts the patient survival at the fourth stage of LUAD, which regulates EZH2, TIGAR, Lico A, etc. that affect lung cancer." (PMID 32428028, 2020). "To test whether EZH2 affects the sensitivity of LUAD cells to EGFR-TKIs, we knocked down EZH2 expression in lung cancer cells using siRNA and subjected the cells to the CCK8 assay after exposure to different concentrations of gefitinib for 24–48 h." (PMID 33276757, 2020). "In NSCLC, EZH2 inhibitors could effectively enhance the sensitivity to etoposide in patients with BRG1- and EGFR-mutant lung cancers." (PMID 33276757, 2020).
lung cancer (continued). "Therefore, we believe that the combined detection of EZH2 with EGFR, KRAS, and BRAF has more advantages in the diagnosis and treatment of lung cancer." (PMID 33299862, 2020). "In lung cancer, the expression of lncRNA-SVUGP2 could be suppressed by EZH2 and further promoted the occurrence and development of lung cancer via Wnt/β-catenin pathway." (PMID 32587476, 2020). "Knockdown of EZH2 reduced the CCL5 protein secretion and therefore inhibited the macrophage recruitment, finally leading to the decreased invasion and metastasis ability of lung cancer cells." (PMID 31855281, 2020). "We studied the mechanisms implicated in the progression and invasion of lung cancer (apoptosis, invasion capacity and vimentin expression) due to CSE and EZH2-mediated, using A549 rather than 16HBE in “in vitro”." (PMID 31666665, 2019). "Furthermore, the administration of lung cancer cells with GSK343, a well-established EZH2 inhibitor, led to a significant reduction in cellular motility and migration, indicating a functional relevance of EZH2 in our system." (PMID 30555330, 2018). "We verified that linc00673 could directly bind with EZH2 in lung cancer cell lines by means of RIP and RNA-pulldown assays, which suggested that linc00673 and EZH2 could regulate downstream genes at the transcriptional level." (PMID 28423732, 2017). "Previous studies have shown that the dysregulated expression of EZH2, one of the three core components of PRC2 (EZH2, SUZ12, and EED), could be a biomarker in diverse cancers, such as lung cancer, gastric cancer, hepatocellular carcinoma and cervical cancer." (PMID 28423699, 2017). "For example, curcumin inhibits the transcription of the ezh2 gene; curcumin degrades EZH2 mRNA through elevated levels of miR-101 and miR-let 7c; and the decreased level of EZH2 resulted in the downregulation of NOTCH1 in lung cancer." (PMID 27049834, 2016). "EZH2 is a key component of the PCR2 complex and is frequently overexpressed in a wide variety of human malignancies such as breast, prostate, gastric and lung cancers." (PMID 27472460, 2016). "To explore whether EZH2 was related to the function of LncRNA FOXF1-AS1, we analyzed the expression of EZH2 in lung cancer tissues compared with normal tissues, showing that EZH2 expressed highly in tumor tissues." (PMID 27577075, 2016). "Taken together, these results suggest that EZH2 is an important target of curcumin in lung cancer, but it is not the only target." (PMID 27049834, 2016). "There was a reciprocal regulation between EZH2 and NOTCH1 in lung cancer cells." (PMID 27049834, 2016). "In CRC and lung cancer, high EZH2 expression was not correlated with the reported clinicopathological features." (PMID 26683709, 2016). "As EZH2 has histone methyltransferase activity with substrate specificity for H3K27 22, the effect of EZH2 knockdown on miR-139 and PDE2A expression was analyzed in lung cancer cells." (PMID 26256448, 2015). "In NSCLC tissues, many onco-miRs/tumor suppressor-target or tumor suppressor-miRs/onco-target pathways have been demonstrated to participate in the tumorigenesis of lung cancer, including miR7/BCL2 axis, miR-99b/FGFR3 axis, miR-101/EZH2 axis, miR-192/RB1 axis and miR-196/HOXA5 axis." (PMID 25012722, 2014). "HOTAIR-regulated EZH2-dependent methylation of non-histone substrates in lung cancer cells can be explored using a proteomic survey of the methylated proteins with or without inhibition of HOTAIR and/or EZH2." (PMID 25491133, 2014). "IDH2 inhibitors are naturally being developed for IDH2-mutant leukemia, EZH2 inhibitors are being studied in EZH2-altered B-cell lymphoma, and our BET inhibitors are actively being studied in BET-rearranged lung cancer and BET-rearranged head and neck cancer (so-called NUT midline carcinoma)." (PMID 25593599, 2014).
lung cancer (continued). "MALAT1 can interact with the histone methyltransferase EZH2, promoting the methylation of histone H3K27 in the promoter regions of certain tumor suppressor genes, inhibiting the expression of these genes and promoting the invasion and metastasis of lung cancer cells." (PMID 41394878, 2025). "Targeting EZH2, MDM2, and other identified proteins may inhibit tumor growth, enhance treatment responsiveness, and disrupt critical cancer pathways, offering promising strategies for the development of effective lung cancer therapies." (PMID 40070571, 2025). "Our study revealed the molecular mechanism of interrelation between HIF‐1α and EZH2 and provides a pharmacological basis for the dual targeting of HIF‐1α and EZH2, and the dual‐targeting compound DYB‐03 may be a promising candidate for the treatment of various cancer, such as lung cancer." (PMID 38072662, 2024). "Suffice to say, the single use of EZH2 inhibitors in treating lung cancer patients may not be effective based on our findings that EZH2 inhibition failed to block A549 spheroid growth." (PMID 37992808, 2024). "Furthermore, we found a negative correlation between the HIF‐1α and EZH2 dependency scores in lung cancer cell lines (Spearman cor =−0.24, p = 0.009), suggesting that lung cancer cells selectively rely on HIF‐1α or EZH2 for survival." (PMID 38072662, 2024). "However, it has been reported that suppressing the activity of SAH hydrolase (such as DZNep) or hindering the linkage of EZH2 with SAM can significantly downregulate the global H3K27me3, leading to the inhibition of tumor cell (such as breast, bladder, and lung cancers) survival." (PMID 32448308, 2020). "Furthermore, previous meta-analyses did not specifically explain the prognostic relationship between EZH2 and lung cancer, or no bioinformatics evidence was used to support it." (PMID 33299862, 2020). "Several studies demonstrated co-inhibition of both EZH2 and EGFR could show a synergic effect on tumor growth inhibition through inducing autophagy and increasing apoptosis in colon cancer cells, gastric cancer cells, and lung cancer cells." (PMID 32723346, 2020). "However, although EZH2 has widely known to be a critical regulator of lung cancer progression, the definite mechanism of EZH2 in macrophage recruitment of lung cancer was not fully elucidated." (PMID 31855281, 2020). "Generally, relatively little is known about epigenetic regulation of NRF2 action, but, interestingly, one paper reported that the transcription factor was repressed by EZH2 in lung cancer cells; an interaction with UTX has not been reported to the best of our knowledge." (PMID 30987376, 2019). "Since the inhibition of Ezh2 has recently been shown to amplify TNF-α–induced NF-κB signaling and inflammation in normal intestinal epithelium, it is plausible that our findings in lung cancer can be extended to other Kras-driven epithelial malignancies, such as pancreatic ductal carcinoma." (PMID 30487290, 2018). "Thus, in this study, we tested the hypothesis that down regulation of miR-21 and EZH2 expression level via anti-miR-21 or EZH2 shRNA reduce LCSC growth, thereby altering lung cancer development and progression." (PMID 29156731, 2017). "Moreover artificial overexpression of EZH2 increased the tolerance of lung cancer cells against curcumin; however these cells were not able to survive curcumin treatment." (PMID 27049834, 2016). "In this study, we demonstrated the inhibitory effect of PPI on lung cancer cell growth through stress-activated protein kinase/c-Jun N-terminal kinase (SAPK/JNK)-mediated inhibition of NF-kB subunit p65 and DNMT1 protein levels, subsequently; this resulted in the reduction of EZH2 gene expression." (PMID 27421653, 2016).
lung cancer (continued). "When analysis was restricted to stage I lung cancer, we found that the combined HR (2.51) was larger than the combined HR for all 10 eligible studies of stages I-III (1.68), suggesting that EZH2 expression could be an important prognostic factor for early-stage lung cancer." (PMID 26754405, 2016). "Interestingly, mIR-138 has recently been identified as a miRNA that targets KMT6 (EZH2), and in a study of miRNA profiles for never-smoker lung cancers, this miRNA was a uniquely downregulated miRNA compared to tumors derived from smokers." (PMID 24212667, 2011). "In addition, consistent with our findings in breast, prostate, and colon cancers, tumoral USP22 and EZH2 protein expressions exhibited a strong positive correlation, and both were inversely correlated with tumoral β2M expression and with CD8+ T lymphocytes infiltration in lung cancer." (PMID 41252204, 2025). "In this study, we used A549 lung cancer cells and noncancerous BEAS-2B epithelial cells as model systems and applied long-read ChIA-PET to map global chromatin interactions associated with different factors, including RNA polymerase II (RNAPII), CCCTC-binding factor (CTCF), EZH2, and H3K27me3." (PMID 36702236, 2023). "However, neither curcumin nor RNAi against EZH2 or NOTCH1 could induce cell apoptosis in the lung cancer cells that we investigated." (PMID 27049834, 2016). "Thus, deregulation or inactivation of EZH2 and DNMT1 could be important drivers of development, progression of tumor, and may be of therapeutic benefit for patients with malignancies including lung cancer." (PMID 26362062, 2015). "According to our results, the correlation between the expression of EZH2 and the expression of EGFR in lung carcinoma is not statistically significant." (PMID 33299862, 2020). "Similarly, the levels of EZH2 were increased in lung cancers as compared with normal tissues and its levels were correlated to the ones of the lncRNA MSTO2P, (a new positive regulator of EZH2 whose mechanism is unknown), data which were coherent since lncRNA MSTO2P can positively regulate EZH2." (PMID 31861179, 2019). "reports that DZNep globally inhibits histone methylation and is not necessarily specific to EZH2 25, the effect of EZH2 knockdown on miR-139 and PDE2A expression was analyzed in two lung cancer cell lines." (PMID 26256448, 2015). "Results showed a significant decrease in EGFR, CBP, and SMARCB1 at mRNA and protein levels, and a significant increase in mRNA of EZH2, but no significant change in protein levels for EZH2, suggesting that both MEOX2/GLI-1 modulate these tumor and epigenetic markers in lung cancer A549 cells." (PMID 39971779, 2025). "Additionally, the negative feedback regulation between EZH2 and HIF‐1α is confirmed in lung cancer patient tissues and a database of cell lines." (PMID 38072662, 2024). "In addition, EZH2 has been shown to enhance the expression of CCL5 to promote recruitment of macrophages and invasion in lung cancer, although the mechanism was not clearly identified." (PMID 36038549, 2022).
melanoma (268 papers, 2009 to 2026). A malignant, usually aggressive tumor composed of atypical, neoplastic melanocytes. "EZH2 activating mutations or copy number alterations in melanoma result in transcriptional silencing of tumor suppressor genes, immune response genes, and differentiation factors, contributing to poorer overall survival and metastasis-free survival." (PMID 39984702, 2025). "We describe a patient with multiply recurrent melanoma harboring an EZH2 A692V missense mutation—a pathogenic variant most commonly described in follicular lymphoma—who experienced a prolonged relapse-free survival with adjuvant tazemetostat." (PMID 39984702, 2025). "In melanoma preclinical studies, EZH2 overexpression has been implicated in the escape of immune surveillance, silencing of tumor suppressors and apoptosis pathways, and shaping the interactions between melanoma cells and the microenvironment." (PMID 39984702, 2025). "EZH2 is overexpressed or mutated in many cancer types, including melanoma, but the clinical success of EZH2-targeted therapies to date has been limited to epithelioid sarcoma and follicular lymphoma." (PMID 39984702, 2025). "MITF levels are inversely correlated with transcription factor 4 (TCF4) and EZH2, which promote the mesenchymal-like state of melanoma associated with the suppression of antigen presentation." (PMID 40108693, 2025). "Activating mutations of EZH2 are identified in approximately 3% of melanomas, contributing to tumor progression." (PMID 40427015, 2025). "Further studies are needed to determine which EZH2 or SMARCB1 alterations are most predictive of response to EZH2-targeted therapies and the best administration sequence of these drugs in EZH2-mutated melanomas." (PMID 39984702, 2025). "For example, FOXC2-AS1 promotes melanoma cell proliferation by silencing the tumour suppressor gene cyclin-dependent kinase inhibitor 2B CDKN2B (which encodes p15INK4b) through an EZH2-dependent recruitment mechanism." (PMID 41463281, 2025). "Here, we describe a pediatric patient with multiply relapsed melanoma harboring an EZH2 A692V missense mutation, treated adjuvantly with the EZH2 inhibitor tazemetostat, who experienced a prolonged relapse-free survival." (PMID 39984702, 2025). "Next-generation sequencing has identified EZH2 overexpression and/or alterations across several cancer types—including melanoma—and is associated with aggressive disease." (PMID 39984702, 2025). "In melanoma, EZH2 expression is associated with a high proliferation rate due to repressive H3K27 methylation, and its deficiency can have a proapoptotic effect by normalizing CDKN1A locus acetylation and eliminating histone deacetylases." (PMID 40427015, 2025). "The combination of EZH2 with DNA methylation causes the silencing of important suppressor genes which drives melanoma tumor development." (PMID 40959208, 2025). "In melanoma and bladder cancer models, combining EZH2 inhibitors with anti-cytotoxic T-lymphocyte-associated antigen 4 (CTLA-4) therapy demonstrated a direct role for EZH2-mediated T-cell reprogramming in enhancing anti-tumor immunity." (PMID 40040700, 2025). "The loss of miR‐26a in melanoma enhances cell cycle progression, and EZH2 overexpression is associated with more invasive and aggressive tumour phenotypes." (PMID 39823244, 2025). "Here, we describe a pediatric patient with multiply relapsed melanoma harboring an EZH2 mutation, who achieved a prolonged relapse-free survival following adjuvant treatment with tazemetostat." (PMID 39984702, 2025). "In this study, we analyzed the copy numbers of EZH2 in 547 melanoma tissue samples and discovered that EZH2 amplification is associated with poor prognosis of MM patients." (PMID 39518098, 2024). "The presence of EZH2 somatic mutations has been observed in a subset of melanoma cases, as shown in The Cancer Genome Atlas (TCGA) dataset." (PMID 39304771, 2024).